LIPE (lipase E, hormone sensitive type)
Diseases named in the same sentence as LIPE in open-access papers:
LIPE is named in the same sentence as 92 diseases in open-access papers, as found by Europe PMC text mining. Sharing a sentence is not in itself a finding about the gene and the disease. The quoted sentences say what the papers report.
Obesity (79 papers, 2006 to 2025). Accumulation of substantial excess body fat. "Interactome network analysis of the lower expressed genes in FTO obesity-risk genotype suggests that under normal conditions, DECR1 (dienoyl-CoA reductase), LIPE, LDHB, SOD2, ATP5B, and J are central elements in maintaining connectivity." (PMID 32316277, 2020). "Hormone sensitive lipase (HSL) promoter (LIPE-60 C > G) polymorphism has been found to be involved in hepatic steatosis, obesity, diabetes and dyslipidemia." (PMID 23688034, 2013). "Importantly, it was estimated that 40-70% of genetic factors that are related to cancer development were found to be strongly associated with obesity, including those involved in lipid metabolism, such as LPIN1, hormone-sensitive lipase LIPE and fatty acid synthase FASN12,38,39." (PMID 33203880, 2020). "Moreover, we propose a number of genes as candidates for fat content inpigs (LIPE, LXRA, HP), which were previously investigated in termsof human obesity." (PMID 29658965, 2018).
Insulin resistance (54 papers, 2008 to 2025). Increased resistance towards insulin, that is, diminished effectiveness of insulin in reducing blood glucose levels. "Germline variants in LIPE are known to cause a recessive syndrome characterized by multiple symmetric lipomatosis, partial lipodystrophy, and insulin resistance." (PMID 35207755, 2022).
Hepatic steatosis (23 papers, 2013 to 2025). Steatosis is a term used to denote lipid accumulation within hepatocytes. "We found that feeding had a significant positive effect on ribosome occupancy of 49 mRNAs associated with hepatic steatosis (e.g., LIPE, LPL), but this effect was blunted in the liver of rats fed a WD." (PMID 36387860, 2022). "In humans, carriers of a frameshift deletion of exon 9 in the LIPE gene, encoding for HSL, were characterized by metabolic dysfunction, including dyslipidemia, hepatic steatosis, systemic insulin resistance, and diabetes." (PMID 30086728, 2018). "PRKAA1 and LIPE in Ethiopian humans and PPARA in Tibetan humans are both associated with lipid metabolism, which can be negatively impacted by chronic hypoxia as it increases the risk of developing fatty liver disease." (PMID 31154977, 2019).
Cachexia (19 papers, 2014 to 2024). Severe weight loss, wasting of muscle, loss of appetite, and general debility related to a chronic disease. "Since intramuscular lipid metabolism can be compromised during cachexia, we investigated the expression of Lipase E hormone sensitive (LIPE), known to be involved in intramuscular lipid accumulation." (PMID 35392166, 2022).
breast cancer (15 papers, 2017 to 2026). A primary or metastatic malignant neoplasm involving the breast. "The reduced expression of lipolytic-related genes such as LIPE was also observed in samples from high-risk patients, which was unexpected but nevertheless observed in co-cultured breast cancer cells with adipocytes, alluding to a unique adipocyte phenotype in this environment." (PMID 35978404, 2022). "We also observed that the expression of hormone-sensitive lipase (LIPE) was significantly lower in high-risk PPAT samples than in low-risk samples, which has also been described in breast cancer-associated adipocytes." (PMID 35978404, 2022). "Analysis of The Cancer Genome Atlas (TCGA) showed that AKR1C1, AQP7, CD36, and LIPE display low genomic alteration frequency in breast cancer, and only CD36 expression has prognostic value (P = 0.005)." (PMID 33083529, 2020). "Therefore, elevated levels of CD36, AQP7, LIPE, and AKR1C1 in mammary epithelial cells may serve as promising indicators for identifying high-risk breast cancer groups." (PMID 40868150, 2025). "AMPK (involved LIPE and LEP) and PPAR (involved PLIN1) were two significantly enriched pathways in luminal A breast cancer." (PMID 35692369, 2022). "We also observed reduced expression of LIPE and FABP4 genes in CAAs in comparison to adipocytes, which was also described in types of cancer (such as breast cancer) and might seem to be inconsequential." (PMID 37316878, 2023). "In addition, we found that AMPK (involved LIPE and LEP) (p value = 0.003440464) and PPAR (involved PLIN1) (p value = 0.018732701) were two significantly enriched pathways in luminal A breast cancer." (PMID 35692369, 2022). "In addition, based on functional enrichment of DEmRNAs coexpressed with DElncRNAs, we found that AMPK (involved LIPE and LEP) and PPAR (involved PLIN1) were two significantly enriched pathways in luminal A breast cancer." (PMID 35692369, 2022).
diabetes (15 papers, 2013 to 2024). "We found many previously reported associations, such as associations between leptin and sex and CRP and BMI, and also new associations that are biologically plausible, such as LIPL and LIPE with diabetes status." (PMID 38307861, 2024). "The strong evidence supporting a causal role for dyslipidemia in diabetes comes from genetic studies of rare mutations in ABCA1, LIPE, LPL, and LRP6, showing that these lipid genes are also linked to hyperglycemia or diabetes." (PMID 35740449, 2022).
pancreatic cancer (12 papers, 2018 to 2024). "Although LIPE, MT2A, PLD4 and ZNF589 have been studied in other tumours, their relationship with tumour-associated macrophages in pancreatic cancer remains to be investigated." (PMID 37469705, 2023). "The results showed that APOBEC3C and LIPE were highly expressed in pancreatic cancer tissues." (PMID 37469705, 2023).
lipodystrophy (7 papers, 2020 to 2025). A congenital or acquired disorder characterized by abnormal loss or redistribution of the adipose tissue in the body. "LIPE encodes the key lipolytic enzyme hormone-sensitive lipase (HSL), and LIPE pathogenic variants leading to lipodystrophy act through loss-of-function mechanisms." (PMID 35046902, 2021).
prostate carcinoma (5 papers, 2020 to 2025). A carcinoma that arises from epithelial cells of the prostate gland. "Monoacylglycerol lipase, functioning with hormone-sensitive lipase (LIPE) to hydrolyze intracellular triglyceride stores to fatty acids and glycerol, is highly expressed in prostate cancer and is related to the EMT process." (PMID 32547948, 2020).
familial partial lipodystrophy (4 papers, 2022 to 2025). "Regarding Familial Partial Lipodystrophy (FPLD), the main subgroups, FPLD2 to 6, are associated with pathogenic variants in LMNA, PPARG, PLIN1, CIDEC and LIPE respectively, whereas FPLD1 is thought to be of polygenic origin." (PMID 38678257, 2024). "Partial lipodystrophy syndromes are classified into Familial Partial Lipodystrophy (FPLD) including FPLD1 (Köbberling syndrome), FPLD2 (Dunnigan syndrome, due to mutations in the LMNA gene), FPLD3 (PPARG gene), FPLD4 (PLIN1 gene), FPLD5 (CIDEC gene), FPLD6 (LIPE gene) gene mutations." (PMID 41341138, 2025).
lipomatosis (4 papers, 2021 to 2022). A neoplastic process characterized by diffuse overgrowth of mature adipose tissue. "In humans, bi-allelic null mutations in the LIPE gene, encoding the hormone-sensitive lipase (HSL), is associated with a complex AT phenotype including fat redistribution, multiple symmetric lipomatosis (excess fat accumulation) and partial lipodystrophy." (PMID 35250856, 2022). "More importantly, LIPE encodes the rate-limiting enzyme of lipolysis, and homozygous null mutation of LIPE results in marked inhibition of lipolysis, leading to multiple symmetric lipomatosis." (PMID 34900686, 2021). "In specific genetic forms of partial lipodystrophy, due to MFN2 or LIPE biallelic pathogenic variants, fat overgrowth may lead to massive pseudo-lipomatous regions in upper body and proximal limb areas, leading to the diagnosis of multiple symmetric lipomatosis." (PMID 35046902, 2021). "Therefore, multiple symmetric lipomatosis could be, at least in MFN2 and LIPE-related forms, an exacerbated form of partial lipodystrophy." (PMID 35046902, 2021).
liposarcoma (4 papers, 2017 to 2021). A usually painless malignant tumor that arises from adipose tissue. "Although PNPLA2 deletion has been reported in well differentiated liposarcoma and LIPE deletion, in DDLS with poor outcome, neither ATGL deficiency nor HSL deficiency reportedly causes liposarcoma in mice." (PMID 28459858, 2017). "Recently, Wu and collaborators demonstrated that double knockouts of PNPLA2 and LIPE in mice, but not their single knockouts, down-regulated metabolic genes, including those involved in fatty acid and lipid metabolism, and the mice spontaneously developed liposarcoma in brown adipose tissue." (PMID 32158531, 2020).
lipoma (3 papers, 2020 to 2025). A benign, usually painless, well-circumscribed lipomatous tumor composed of adipose tissue. "The presence of lipomas is common, particularly in cases associated with variants of LMNA, MFN2, or LIPE." (PMID 40452043, 2025). "The expression of both LIPE and PNPLA2 showed a gradual decrease from lipomas towards DDLPS, with significantly lower expression already in WDLPS/ALT compared to lipomas." (PMID 32158531, 2020).
partial lipodystrophy (3 papers, 2021 to 2022). Loss and redistribution of subcutaneous and/or visceral adipose tissue from specific regions of the body. "LIPE biallelic pathogenic variants may also lead to pseudo-lipomatous forms of partial lipodystrophy." (PMID 35046902, 2021).
Lewy body diseases (1 paper, 2024). "Our study highlights fatty acid turnover as a therapeutic target for Lewy body diseases and support LIPE as a promising target in males." (PMID 38971480, 2024).
Lipedema (1 paper, 2024). Disorder of adipose tissue characterized by symmetric and bilateral enlargement of the lower extremities due to abnormal deposition of subcutaneous fat often in obese women. "E2 treatment significantly increased the gene expression of LIPE (3-fold) and STS (1.5-fold) in HD-treated lipedema cells compared to untreated cells." (PMID 38791004, 2024). "CYP19A1 and LIPE gene expressions were significantly increased in estrogen-treated healthy ASCs and spheroids, respectively, while estrogen upregulated the expression of PPAR-Υ2 and ERα in estrogen-treated lipedema-differentiated adipocytes and spheroids." (PMID 38791004, 2024).
macular degeneration (1 paper, 2023). Loss of vision in the central portion of the retina (macula), secondary to retinal degeneration. "Moreover, it is possible that combinations of these or other LIPE allele variants with other genes predisposing to retinal dystrophies or degenerations (including macular degeneration), may exacerbate retinal pathology in some individuals." (PMID 37198396, 2023).
MERRF syndrome (1 paper, 2025). A rare mitochondrial oxidative phosphorylation disorder characterized by myoclonic seizures, ataxia, generalized epilepsy, muscle weakness and ragged red fibers in the muscle biopsy. "Genetic investigations have identified familial cases associated with mutations in mitofusin 2 (MFN2) and hormone-sensitive lipase (LIPE) genes, as well as mitochondrial DNA variants linked to myoclonic epilepsy with ragged red fibers syndrome (MERRF syndrome)." (PMID 40746792, 2025).
osteosarcoma (1 paper, 2021). A usually aggressive malignant bone-forming mesenchymal neoplasm, predominantly affecting adolescents and young adults. "Among them, the expression of MYH6 and SULT4A1 in osteosarcoma was higher than that in control group, while the expression of LIPE, ACTG2, KLF4, and TF was decreased." (PMID 34104648, 2021).
soft tissue sarcoma (1 paper, 2017). A malignant neoplasm arising from muscle tissue, adipose tissue, blood vessels, fibrous tissue, or other supportive tissues excluding the bones. "In addition, copy number analysis for 265 patients with soft tissue sarcoma from the TCGA dataset was performed to test the hypothesis that PNPLA2 and LIPE might be tumor suppressors in some tissues." (PMID 28459858, 2017).
synucleinopathy (1 paper, 2024). A neurodegenerative disease that is characterized by the abnormal accumulation of aggregates of alpha-synuclein protein in neurons, nerve fibers or glial cells. "We used heterozygous LIPE knockdown (LKD) mice to evaluate whether a reduction in LIPE level has beneficial effects on synucleinopathy and motor phenotypes of 3K αS mutant mouse." (PMID 38971480, 2024).
thymoma (1 paper, 2021). A neoplasm arising from the epithelial cells of the thymus. "Cox regression analysis showed that low expression of LIPE was a prognostic risk factor for thymoma." (PMID 34104648, 2021). "The nomogram showed that low expression of LIPE was a risk factor for predicting the overall survival time of thymoma at 5 and 8 years." (PMID 34104648, 2021). "This study identified key genes related to the prognosis of thymoma, including LIPE, MYH6, ACTG2, KLF4, SULT4A1, and TF." (PMID 34104648, 2021). "By screening the DEGs that had a significant impact on the prognosis of thymoma, we identified LIPE, MYH6, ACTG2, KLF4, SULT4A1, and TF as key genes." (PMID 34104648, 2021). "DNA and RNA methylation genes are commonly studied as biomarkers, which also seems to be a way for LIPE to participate in the development of thymoma." (PMID 34104648, 2021). "The results may be helpful to understand the pathogenesis of thymoma and identify LIPE as a potential new therapeutic target through bioinformatics analysis." (PMID 34104648, 2021). "LIPE was also predicted as a new prognostic marker of thymoma in other studies." (PMID 34104648, 2021). "LIPE, MYH6, ACTG2, KLF4, SULT4A1, and TF were the key genes affecting the prognosis of thymoma." (PMID 34104648, 2021).
tuberculosis (1 paper, 2019). A chronic, recurrent infection caused by the bacterium Mycobacterium tuberculosis. "The data from this study imply that LipE is involved in the lipid metabolism of M. tuberculosis during infection." (PMID 31636137, 2019).
cancer (57 papers, 2006 to 2025). A tumor composed of atypical neoplastic, often pleomorphic cells that invade other tissues. "RCC tissues that successfully generated organoids highly expressed genes associated with stemness (WNT6/11, FZD8/9 and JAG2), cell matrix (MMP2, COL1A1), fatty metabolism (ACOT2, LIPE) and cancer development (TGFB1, SMAD6/7, EGF and FGF1)." (PMID 35802820, 2022). "The mRNA levels of LIPE have been shown to be significantly increased in the adipose tissue of cancer patients." (PMID 30328513, 2019). "Similarly, we observed that all tested CRC cells converted adipocytes into cancer-associated adipocytes, which decreased lipid content and the expression of genes that are characteristic of adipocytes (including PPARγ, resistin, adiponectin, FABP4, perilipin, and LIPE)." (PMID 37316878, 2023). "NCEH1 mRNA expression was not different between normal and cancer tissue, whereas LIPE mRNA (which encodes HSL) expression was reduced in cancer tissue." (PMID 35033184, 2022). "For instance, we observe significant negative correlation between the EMT score and the esterification gene (DGAT1) in 4 cancer types (BRCA, COADREAD, KIRC, LUAD), and significant positive correlation with lipase (LIPE) in 3 cancer types (BRCA, COADREAD, PRAD)." (PMID 26725848, 2016).
tumor (34 papers, 2012 to 2025). "This is a very relevant aspect for the possible implication of LIPE in the pathogenic mechanism, as retinoic acid (RA) pathway has well-established tumor suppressor function and its loss contributed to the loss of differentiation in WAT." (PMID 32158531, 2020).
infection (7 papers, 2018 to 2025). The state of being infected such as from the introduction of a foreign agent such as serum, vaccine, antigenic substance or organism. "Our cell and mouse infection data strongly support that LipE is important for M. tuberculosis survival/growth in macrophages and in hosts." (PMID 31636137, 2019). "Our data suggest that LipE functions as a lipase and is important for M. tuberculosis intracellular growth and in vivo infection." (PMID 31636137, 2019). "Together, these results suggest that LipE is important for M. tuberculosis intracellular survival and in vivo infection." (PMID 31636137, 2019). "Among them, eight DEGs (RF00100, NXPH2, SEC61G, GADD45G, TUBAL3, LIPE, CSRNP1, and FAM20A) were shared across different comparison groups after FX0910 infection." (PMID 37982609, 2023).
LIPE also shares sentences with these, for which no sentence is quoted: dyslipidemia (11 papers); type 2 diabetes (8); hyperlipidemia (7); metabolic disorders (7); Hyperinsulinemia (6); lipid metabolic disorders (6); steatosis (5); hypertriglyceridemia (4); atherosclerosis (3); colitis (3); Stroke (3); type 1 diabetes (3); Azoospermia (2); colorectal cancer (2); gastric cancer (2); Glucose intolerance (2); leukemia (2); myocardial infarction (2); ZIKV infection (2); Abdominal obesity (1); acne (1); acquired lipodystrophy (1); acute lymphoblastic leukemia (1); adrenocortical carcinoma (1); adrenocortical tumour (1); Arthritis (1); autosomal dominant polycystic kidney disease (1); Berardinelli-Seip congenital lipodystrophy type 2 (1); bone metastasis (1); cardiomyopathy (1).
A further 36 diseases each share a sentence with LIPE in 1 paper.